RN7SKP5 (RN7SK pseudogene 5)
Gene: Miscellaneous RNA gene on chromosome 13 (46,249,942 to 46,250,213, forward strand). Ensembl gene ENSG00000252854.
Homologues: Orthologues: chimpanzee 7SK (96% identical). Paralogues in human: RN7SKP93 (56% identical), RN7SKP128 (56% identical), RN7SKP85 (56% identical), RN7SKP192 (56% identical), RN7SKP257 (56% identical), RN7SKP15 (55% identical), RN7SKP180 (55% identical), RN7SKP241 (55% identical), RN7SKP37 (55% identical), RN7SKP79 (55% identical), RN7SKP250 (55% identical), RN7SKP30 (55% identical), and 284 more.